KRT19 (keratin 19)
Diseases named in the same sentence as KRT19 in open-access papers (continued):
Sharing a sentence is not in itself a finding about the gene and the disease.
prostate carcinoma (16 papers, 2009 to 2025). A carcinoma that arises from epithelial cells of the prostate gland. "KRT19 expression H-scores were significiantly higher in AA cancer patients compared with EA prostate cancer patients (Wilcoxon test: p<0.05)." (PMID 36033462, 2022). "This study reports on the development of a novel serum protein panel of three prostate cancer biomarkers, Filamin A, Filamin B and Keratin-19 (FLNA, FLNB and KRT19) using multivariate models for disease screening and prognosis." (PMID 29682400, 2017). "A recent study by this group discovered three novel biomarkers, FLNA, FLNB and KRT19 for prostate cancer." (PMID 29682400, 2017). "FLNB and Keratin-19 (KRT19) were identified as very important nodes that were causally influenced by culture conditions of hypoxia and lactic acid in the metastatic prostate cancer cell line, PC-3." (PMID 28344825, 2017). "In PCa, expression of KRT8, KRT18, and KRT19 by tumor cells disseminated to the bone, is associated with a worse prognosis; KRT18 and KRT5 expression correlates with metastases and hormone-escaped prostate carcinomas, respectively." (PMID 36033462, 2022). "A recent study evaluating 500 serum specimens reported the development of a novel serum protein panel of three prostate cancer biomarkers, Filamin A, Filamin B, and Keratin-19 (FLNA, FLNB, and KRT19) using multivariate models for disease screening and prognosis." (PMID 31013716, 2019). "Conversely, in the other study, KRT8, KRT15, KRT19, KRT34, and KRT80 were found to be enriched in African American prostate cancer samples." (PMID 40104216, 2025). "For example, a study that focused on the clinical validation of a serum protein panel consisting of FLNA, FLNB, and KRT19 (keratin 19) found that their expression and PSA in combination were better than PSA alone in identifying prostate cancer." (PMID 38255186, 2023). "We found that depending on age of prostate cancer patients and Gleason score EMT genes with distinctly altered expression are: KRT18, KRT19, MUC1 and COL4A1, CTNNB1, SNAI2, ZEB1 and MMP3." (PMID 29206234, 2017). "Previous work has shown the absence of KRT19 in prostate cancer cells compared to the levels observed in androgen refractory cell lines." (PMID 29682400, 2017).
lung adenocarcinoma (15 papers, 2013 to 2025). A carcinoma that arises from the lung and is characterized by the presence of malignant glandular epithelial cells. "Recent studies have indicated a relationship between KRT19 and the aggressive and metastatic dissemination of lung adenocarcinoma." (PMID 35512017, 2022). "Lung adenocarcinoma patients with high expression levels of ISG15, MMP1, TRPA1, KRT19, and PLAU (red line) were significantly associated with poor survival rates (log rank P value: 2.3e-07, 0.00034, 0.00037, 0.00057, and 0.023, respectively) as compared to those with low expression (black line)." (PMID 35354498, 2022). "Moreover, expression of KRT19 can be elevated by miR-200 to promote the metastasis of lung adenocarcinoma." (PMID 31032367, 2019). "An automated eight-color mIF panel was evaluated to study the TME using seven antibodies, including cytokeratin 19, CD3e, CD8a, CD4, PD-1, PD-L1, F4-80 and DAPI, then was applied in six mice lung adenocarcinoma samples." (PMID 38877529, 2024). "To estimate the survival function of ISG15, MMP1, TRPA1, KRT19, and PLAU, we performed KM plotter analysis generated for groups of lung adenocarcinoma patients based on their expression levels." (PMID 35354498, 2022). "On the other hand, cytokeratin 19‐fragment (CYFRA21‐1) and carcinoembryonic antigen have been used as tumour markers in human lung adenocarcinoma, and reports indicate that sensitivity increases when these markers are measured simultaneously with serum nectin‐4." (PMID 35905293, 2022). "In addition, the same trend was observed in the TCGA dataset, although the statistical value was marginal (P = 0.0613), suggesting that the cooperative expression of KRT19 and HER2 might be correlated with a poor prognosis in lung adenocarcinoma patients." (PMID 28008968, 2016).
follicular adenoma (14 papers, 2006 to 2023). "In the index study, 25.0% of the follicular adenomas showed diffuse expression of cytokeratin 19 by the tumour cells and the remaining 75.0% were either negative or focally positive." (PMID 37455890, 2023). "In differentiating between follicular adenoma, follicular carcinoma, and the follicular variant of PTC, several biomarkers have proved to be applicable, including LGALS, hemoglobin, epsilon 1 (HBE1), cytokeratin-19 (CK-19), and thyroid peroxidase (TPO)." (PMID 27213120, 2016). "Cytokeratin 19 expression was negative in only one (6.3%) of the follicular adenomas but was variably expressed in the remaining fifteen (93.7%) cases." (PMID 37455890, 2023).
thyroid (14 papers, 2010 to 2023). "Gal-3, together with human bone marrow endothelial cell-1 (HBME-1) and Cytokeratin-19 (CK-19), are markers most commonly used to assist in distinguishing different thyroid lesions." (PMID 28471415, 2017). "Among these markers, galectin-3, TG, Ki67 and cytokeratin-19 (CK-19) have been most frequently used in thyroid pathology." (PMID 22188859, 2011).
COVID-19 (12 papers, 2021 to 2026). A disease caused by infection with severe acute respiratory syndrome coronavirus 2. "We further showed that KRT19 had higher levels in COVID-19 as compared to CAP-Bac and NP-Sepsis, but similar levels compared to CAP-Infl and septic shock." (PMID 36829233, 2023). "It was interesting to observe that both severe and moderate COVID-19 patients had elevated KRT19 even four months after acute disease, suggesting a lingering release of the protein into the bloodstream after lung damage." (PMID 36829233, 2023). "In contrast, only two proteins, pleiotrophin (PTN) and keratin-19 (KRT19), were upregulated in COVID-19." (PMID 36829233, 2023). "We thus concluded that WFDC2, GDF15, CHI3L1, and KRT19 were four key proteins related to COVID-19 severity." (PMID 36331721, 2023). "In tissue samples from two out of five COVID-19 patients, on average 2% of KRT19(+) ducts expressed N-protein." (PMID 35769263, 2022). "This dynamic of protein levels in acute and convalescent phase was specific to KRT19 and HGF, as most proteins upregulated in severe COVID-19 during acute phase normalized during convalescence." (PMID 36829233, 2023). "In our study, the critical COVID-19 patients were divided into three phenotypes (α, β, γ) using WFDC2, CHI3L1, and KRT19 on day 1 by latent class analysis." (PMID 36331721, 2023). "Very few proteins had higher levels in COVID-19 compared to sepsis in this study, among them PTN and KRT19." (PMID 36829233, 2023). "The common plasma proteins that were higher in the COVID-19 patients than controls and that were higher in the late recovery group than the early recovery group for phases 1 and 2 were WFDC2, CHI3L1, GDF15, KRT19, and TNFRSF10B." (PMID 36331721, 2023). "The presence of CASP3, EPCAM, KRT19, and TGFA in the red module therefore suggests that one of the key features of the post-COVID-19 airway is the presence of ongoing epithelial injury and repair." (PMID 35151371, 2022). "Proteins linked to inflammation feature less prominently than in acute COVID-19, whereas upregulation of proteins involved in epithelial damage and repair (e.g., the EGFR ligand AREG and the epithelial marker KRT19) persist." (PMID 35151371, 2022). "Interestingly, a set of six proteins had a similar behavior to KRT19 and HGF during the acute phase of COVID-19, except that they reached healthy levels during convalescence." (PMID 36829233, 2023). "Among these proteins, KRT19, TOP2B, AREG, HGF, CKAP4, ITGB6, and NCF2 had a higher expression (> twofold) in plasma samples of severe compared to moderate COVID-19 patients, whereas CLEC4C and LTA were among the few proteins that were expressed at lower levels in severe patients." (PMID 36829233, 2023). "Higher levels of several of these proteins were inversely correlated with viral load, including the cytosolic RNA sensor RIG-I (gene symbol DDX58), chemokines (CCL20 and CCL25), and other proteins (Keratin 19 [KRT19], amphiregulin [AREG]) previously shown to be upregulated in COVID-19 patients." (PMID 36239699, 2022). "Thus, it could be relevant to prospectively monitor KRT19 and HGF in COVID-19, to evaluate their potential value in prognosis of lung impairment post-COVID-19." (PMID 36829233, 2023). "By stratifying the comparison to CAP based on etiology, PTN was consistently higher in COVID-19 compared to both CAP-Infl and CAP-Bac, while KRT19 was only higher when compared to CAP-Bac but not to CAP-Infl." (PMID 36829233, 2023).
pancreatitis (12 papers, 2015 to 2023). Inflammation of the pancreas. "Importantly, the ectopic expression of ST6GAL1 in acinar cells induces a pronounced upregulation in a ductal gene network (in the absence of either pancreatitis or the KRAS oncogene), as evidenced by RNA-Seq results and staining of SC tissues for SOX9, KRT8, and KRT19." (PMID 37643018, 2023).
gastric tumor (11 papers, 2009 to 2025). "Moreover, a recent study assessed that the overexpression of miR-642 decreases the proliferation and migration of gastric tumor cells affecting the KRT19 expression." (PMID 39771533, 2024).
endometriosis (10 papers, 2014 to 2025). The growth of functional endometrial tissue in anatomic sites outside the uterine body. "In 2011, the protein that was found in the urine of endometriosis patients was identified as a cytokeratin-19 fragment, namely, CYFRA 21-1 but the sample size was small (n=16) (Tokushigeet al., 2011)." (PMID 40469991, 2024). "The mean levels of cytokeratin-19 fragments (CYFRA 21-1) in the urine of women with endometriosis were significantly higher in the proliferative phase than in the secretory phase." (PMID 40469991, 2024). "No research has been found that analyzes the cutoff value of cytokeratin-19 fragments (CYFRA 21-1) to creatinine (CYFRA/Cr) urine ratio in endometriosis." (PMID 40469991, 2024). "Another protein obtained from urine and considered as a biomarker for endometriosis is cytokeratin 19 (CK 19)." (PMID 34201813, 2021). "Furthermore, in contrast to normal OSECs, EEC16 did not express N-Cadherin, and RNA-sequencing profiles showed a 342-fold upregulation of an endometriosis marker, keratin 19, in EEC16 compared to OSECs." (PMID 24502583, 2014). "Cytokeratin-19 (CK19) is another molecule that could be used in the detection of endometriosis." (PMID 32143439, 2020). "The levels of cytokeratin-19 fragments (CYFRA 21-1) were significantly higher in the proliferative phase compared to the secretory phase in both the endometriosis and non-endometriosis groups." (PMID 40469991, 2024). "The genes with increased expression (KRT18, KRT19, VIM, and NANOG) were then used in subsequent analyses as “endometriosis confirmatory genes”." (PMID 31717910, 2019). "In parallel with the predecidua changes, various CEC types isolated from patients with endometriosis in our cohort showed different gene expression profiles, represented by typically elevated gene expression of KRT18, NANOG, and VIM or of KRT19 and ESR1." (PMID 31717910, 2019). "As presented inFigure 3, the cytokeratin-19 fragment (CYFRA 21-1) levels to creatinine (CYFRA/Cr) urine ratio was significantly higher in the endometriosis group than the non-endometriotic group (p < 0.05)." (PMID 40469991, 2024). "The level of cytokeratin-19 fragment (CYFRA 21-1) spot urine in women with endometriosis was significantly higher than those without endometriosis." (PMID 40469991, 2024). "Additionally, our study highlights several potential key genes likely involved in the pathogenesis of endometriosis by altering cell migration, such as DKK1, GRB7, MIEN1, PIK3R1, and KRT19." (PMID 39595577, 2024). "Based on the cycle phase, it was found that the average cytokeratin-19 fragment (CYFRA 21-1) to creatinine (CYFRA/Cr) urine ratio was significantly higher in the proliferative phase than the secretory phase in both the endometriosis and non-endometriosis groups." (PMID 40469991, 2024). "Moreover, the cytokeratin-19 fragment (CYFRA 21-1) levels to creatinine (CYFRA/Cr) urine ratio was significantly higher in the proliferative phase compared with the secretory phase in both the endometriosis and non-endometriosis groups." (PMID 40469991, 2024). "Based on the analysis of the cytokeratin-19 fragment (CYFRA 21-1) to creatinine (CYFRA/Cr) urine ratio, it was found that the mean in the endometriosis group was significantly higher than in the non-endometriotic group." (PMID 40469991, 2024).
liver disease (10 papers, 2016 to 2024). "We then analyzed the expression of ccn2, a matricellular protein that is upregulated in fibrotic hepatic disorders and sox9/krt19 expression, markers associated with chronic liver damage." (PMID 34413847, 2021). "Cell-type-specific immunostaining on liver biopsies using a cholangiocyte marker, cytokeratin-19 (CK19), and a hepatocyte marker, HepPar1, also revealed heterogeneous cell populations in human liver diseases." (PMID 38607018, 2024). "By contrast, control CD133-/CD49f- cells expression levels for KRT19, CD133, NANOG, SOX2, OCT4, and TLR4 were independent of IVIG (immune serum from people with HBV+ or HCV+ liver disease) or HBIG incubation." (PMID 37744383, 2023).
chordoma (9 papers, 2010 to 2025). Chordomas are rare malignant tumors arising from embryonic remnants of the notochord in axial skeleton. "The heatmap revealed that MIR5690, SNORD15B, RAB3B were highly expressed in chordoma, along with the generally reported chordoma regulators, such as KRT19, LYST, and EGFR." (PMID 40135815, 2025). "Genes marked on the volcano plot were either implicated earlier in chordoma biology (e.g. keratins—KRT8, KRT18, KRT19, TBXT, LMX1A, and EGFR) or identified by outstanding p-value (e.g. IL11, CD24), high absolute fold-change (e.g. GABRA1) or DMR result (e.g. MNX1)." (PMID 37434245, 2023). "For cell lines that lack Brachyury but have abnormal genetics (like CM319), expression of one or more markers of chordoma including CD24, collagen type II alpha 1, keratin 19, and carbonic anhydrase 3 could offer evidence of chordoma-derived cells." (PMID 21253487, 2010). "Indeed, chordoma was originally described as one of the unique “triple positive” EMA/S100 protein/keratins neoplasia in bone and soft tissue pathology and diffuse immunostaining for wide spectrum cytokeratins, cytokeratin-8, cytokeratin-19, and cytokeratin-18 was demonstrated in this tumour." (PMID 24591762, 2014).
follicular carcinoma (9 papers, 2005 to 2023). "Cytokeratin 19 was expressed in all the follicular carcinoma in the study." (PMID 37455890, 2023).
hepatoblastoma (9 papers, 2013 to 2023). Hepatoblastoma (HB) is a malignant hepatic tumor and is the most common pediatric liver cancer. "Then we specifically investigated the individual genes that indicate hepatocyte differentiation (Cyp2e1), hepatoblastoma markers (Igf2, Afp, Glul, Krt19) and embryonal hepatoblastoma stem cell markers (Dlk1, Epcam and Gpc3)." (PMID 37414763, 2023). "Immunohistochemistry was used to evaluate CD203c, CD326, and cytokeratin-19 expression on three hepatoblastoma tumors." (PMID 36845728, 2023). "The hsa-miR-492 miRNA has been shown to be processed from the keratin 19 gene and upregulated in metastatic hepatoblastoma." (PMID 23601657, 2013). "In particular, hepatoblastoma-like and cytokeratin-19 (CK-19) positive tumours are hypothesised to have originated from liver progenitor cells due to the similarity of their transcriptomic signatures." (PMID 24871369, 2014). "One of the 2 subclasses of hepatoblastoma on gene expression profiling is allied with greater genetic instability (gains of chromosomes 8q and 2p), overexpression of hepatic progenitor cell markers (AFP, Cytokeratin 19, and EpCAM), and upregulated MYC signaling." (PMID 37600579, 2023).
oral squamous cell carcinoma (9 papers, 2011 to 2025). "Moreover, transcriptional up-regulation of KRT14, and down-regulation of KRT15 and KRT19 was observed in oral squamous cell carcinoma (OSCC)." (PMID 36949761, 2023). "Keratins are considered a marker for epithelial stem cells, and increased cytokeratin 19 expression has been shown to be a biomarker of highly invasive oral squamous cell carcinoma with metastatic potential, as well as higher tumor recurrence and lower survival." (PMID 34359613, 2021). "Also, down-regulation of KRT19 in human oral squamous cell carcinoma lines increases the invasive potential, but no other previous studies showed any eventual relationship with the invasive capacity of embryonic cells." (PMID 23717664, 2013).
pancreatic adenocarcinoma (9 papers, 2007 to 2026). "Cytokeratin 19 (CK-19) was studied as a diagnostic marker of adenocarcinoma, which is known as a marker of endometrioid adenocarcinomas, pancreatic adenocarcinoma and head and neck cancer." (PMID 32481524, 2020). "The aim of our study was to investigate cytokeratin-19 fragments (CYFRA 21-1), osteopontin (OPN), and human epididymis protein 4 (HE4) clinical significance in pancreatic adenocarcinoma." (PMID 41683979, 2026).
thyroid neoplasms (9 papers, 2009 to 2023). "The specific objectives were to describe the frequencies of the various thyroid neoplasms and evaluate them for association with age and sex and to describe the immunohistochemical profiles of all the thyroid neoplasms using anti-cytokeratin 19 antibodies." (PMID 37455890, 2023). "For example, a study of 100 benign and 105 malignant thyroid tumors using a panel of 57 molecular markers found an association of tumor pathology with the expression of a subset of markers including cytokeratin 19 (CK19), LGALS3, HBME-1, VEGF, AR, p16, and AURKA." (PMID 25887408, 2015). "In addition to these molecular markers, Galectin-3, Hector Batiffora mesothelial antigen-1 (HBME-1), and cytokeratin-19 have been immunohistochemically analyzed in thyroid tumors." (PMID 23049733, 2012). "One method that may be used to evaluate diagnostically difficult specimens is IHC, as the triad of galectin-3, Hector Battifora mesothelial cell 1 (HBME-1), and cytokeratin 19 (CK19) is well established as a means of differentiating between various thyroid neoplasms." (PMID 26550511, 2015). "On the other hand, AHNAK2, GPX1, KRT19, and SFN show higher expression levels in thyroid tumors." (PMID 37795451, 2023).
cyst (8 papers, 2009 to 2025). A sac-like closed membranous structure that may be empty or contain fluid or amorphous material. "WB analyses of cyst fluid and IHC on corresponding tissue samples confirmed a significant up-regulation of cytokeratin 19 (CK-19/CYFRA 21-1) and S100A13 in cPTC vs. benign lesions." (PMID 25978681, 2015). "After they were expanded, hepatic progenitor cell cultures could undergo differentiation into hepatocyte-like cells that expressed ALB and AAT and stored glycogen, or into cholangiocyte-like cells that formed duct-like cyst structures, expressed KRT7 and KRT19 and acquired epithelial polarity." (PMID 19649295, 2009).
esophageal cancer (8 papers, 2008 to 2026). A primary or metastatic malignant neoplasm involving the esophagus. "KRT19 mRNA levels could be used as an indicator for prognosis evaluation and treatment selection in esophageal cancer patients." (PMID 40070828, 2025). "Results acquired from scRNA-seq advocated for the presence of differential expression of KRT19 between KYSE-30 and parental esophageal cancer cells, thus suggesting that there is inherent paclitaxel resistance in esophageal cancer." (PMID 34745998, 2021).